CST3 (cystatin C)
Diseases named in the same sentence as CST3 in open-access papers (continued):
Sharing a sentence is not in itself a finding about the gene and the disease.
heart failure (continued). "In the Kaplan-Meier analysis, the incidence of MACEs (Log-rank = 18.864, P < 0.001), cardiac death (Log-rank = 7.286, P = 0.007), TVR (Log-rank = 5.103, P = 0.024), and heart failure (Log-rank = 5.167, P = 0.023) was higher in the high cystatin C group than that in the low cystatin C group." (PMID 31317040, 2019). "Renal impairment is clearly an independent risk factor for cardiovascular disease and a close relationship has been established between cystatin C and various subsets of cardiovascular diseases, including coronary heart disease, acute coronary syndrome and heart failure." (PMID 29254149, 2017). "A few studies have demonstrated that cystatin C could provide more precise prediction of WRF than SCr in patients with heart failure." (PMID 26107522, 2015). "Data are needed to better define the relationship between cystatin C and ventricular remodeling, which may clarify its relationship with heart failure and cardiovascular mortality and elucidate new mechanisms which may lead to development of novel therapies." (PMID 21977320, 2011). "Some studies have indicated that serum cystatin C is a predictor of AKI and death in critically ill patients with acute cerebral infarction, acute myocardial infarction, heart failure, or sepsis." (PMID 35054276, 2022). "Identifying common markers for heart failure and renal dysfunction, such as EV CD14 and Cystatin C, is of interest because of the multifactorial feedback pathways linking the heart and kidneys." (PMID 32648717, 2020). "The aim of this study was to investigate the predictive value of single and repeated measurements of GDF-15 compared to Cystatin C and CRP for incidence of heart failure (HF) and death due to coronary heart disease (CHD) in the general population." (PMID 29771963, 2018). "In the current study, we aimed to combine the biomarkers of heart failure (BNP and sST2) and renal injury (NGAL and cystatin C) in diagnosis of AKI in patients with STEMI." (PMID 25853556, 2015). "In this single center study, we found that the biomarkers of heart failure (BNP and sST2) and renal injury (NGAL and cystatin C) at presentation were predictive of AKI within 48 hours in patients with STEMI undergoing primary PCI." (PMID 25853556, 2015). "In this study of STEMI patients undergoing primary PCI, the biomarkers of heart failure (BNP and sST2) and renal injury (NGAL and cystatin C) at presentation were predictive of AKI." (PMID 25853556, 2015). "Interestingly, high cystatin C levels had similar predictive value for adverse clinical outcomes in individuals with or without microalbuminuria, suggesting that the association between higher cystatin C concentrations and risk of heart failure is not solely mediated by microalbuminuria." (PMID 20676281, 2009). "The age, number of members of the household, smoking index, New York Heart Association (NYHA) classification, NEUT%, TC, LDL-C, BUN, creatinine, cystatin-C, TBIL, DBIL and BNP showed significantly positive correlation with HAM-D24 score in hospitalized heart failure patients." (PMID 27955661, 2016). "A prospective observational longitudinal study was conducted in order to evaluate renal function using serum cystatin C (Cys C) and estimated glomerular filtration rate (GFR) after 35 sessions of EECP treatment in 30 patients with chronic stable angina and/or heart failure." (PMID 24021027, 2013). "The smoking index, platelet counts, plateletcrit, NEUT%, TC, triglyceride, LDL-C, apolipoprotein B, BUN, creatinine, cystatin-C, BNP and HAM-D24 score were significantly higher in heart failure patients with depression when compare with those without depression." (PMID 27955661, 2016).
Alzheimer disease (56 papers, 2012 to 2025). A progressive, neurodegenerative disease characterized by loss of function and death of nerve cells in several areas of the brain leading to loss of cognitive function such as memory and language. "Elevated cystatin-C levels in patients with CKD have also been correlated with an increased risk of developing Alzheimer’s disease." (PMID 40002752, 2025). "Recent studies have implicated CST3 dysregulation in various neurological disorders, including Alzheimer’s disease and cerebral small vessel disease, which shares pathological similarities with CADASIL." (PMID 38892848, 2024). "As few studies have found this association in MDD, BD, or SCZ, cystatin C appeared to be involved in amyloid-like brain dysfunction such as Alzheimer’s disease, cognitive disorders, and epilepsy." (PMID 39717378, 2024). "Serum Cystatin C level, an indication of kidney function, has been implicated in the pathogenesis of Alzheimer’s disease and cognitive impairment." (PMID 37207178, 2023). "In the central nervous system, cystatin C colocalizes with β-amyloid plaques and cystatin C has neuroprotective properties, inspiring research into its association with Alzheimer’s disease and other dementias." (PMID 37323925, 2023). "Previous studies have reported the associations of CST3 with some age‐related disorders, like pulmonary fibrosis, age‐related macular degeneration, and Alzheimer's disease." (PMID 37723992, 2023). "In the neurological disease overlay, CST3 was associated with area of amyloid-beta plaques, early onset Alzheimer’s disease, progressive cognitive impairment, and loss of hippocampal neurons." (PMID 36561122, 2022). "Increased expression of cystatin C in cerebrospinal fluid has been highlighted in many neurodegenerative disorders, including Alzheimer’s disease, and it was suggested to be of diagnostic interest." (PMID 34528139, 2022). "It has been shown that Cys C co-deposits with Aβ in Alzheimer’s disease patients’ brains and the association between cystatin C and Aβ demonstrate a specific, saturable, and high-affinity binding between cystatin C and both Aβ1–42 and Aβ1–40." (PMID 35566501, 2022). "We applied the method for obtaining isogenic cells homozygous for variant B cystatin C, a recessive risk factor for age-related macular degeneration and Alzheimer’s disease, in both induced Pluripotent Stem Cells (iPSCs) and a human RPE cell line." (PMID 30655567, 2019). "Human cystatin C has been implicated in Alzheimer’s disease as suggested by the genetic linkage of a cystatin C polymorphism with late onset disease and that cystatin C colocalizes with amyloid-β in plaques associated with Alzheimer’s disease." (PMID 31239483, 2019). "Domain swapping has also been associated with pathological aggregation of proteins, as in serpinopathies, Alzheimer’s disease and the more related case of cystatin C, whose Leu68Gln mutation is responsible for another hereditary amyloidosis." (PMID 29069428, 2018). "Cystatin C, which has a neuroprotective role in Alzheimer's disease, was found secreted in association with exosomes." (PMID 28912682, 2017). "A study of 463 patients with Alzheimer’s disease conducted in China indicated that higher serum cystatin C may be linked with worse cognitive performance." (PMID 38132490, 2023). "Furthermore, five proteins (IGHV3.9, PRG4, VWF, ALB and CST3) were significantly associated with ESR values, with CST3, a protein active in neurodegenerative (Alzheimer’s Disease) and demyelinating (multiple sclerosis) neurological conditions." (PMID 35033099, 2022). "In addition, a common polymorphism of the cystatin C gene has been linked to risk of Alzheimer's disease." (PMID 34616751, 2021). "Cystatin C is highly expressed in the brain and cerebrospinal fluid (CSF) (Löfberg and Grubb, 1979), and it is indicated to play many roles in the risk and pathobiology for Alzheimer's disease (AD)." (PMID 35153722, 2021).
Alzheimer disease (continued). "In addition, many genes closely related to neurological diseases, such as Got1, ApoE, Gm2a, have been found to interact with TET1 in OPCs; and Cst3 is associated with dementia in Lewy body disease and Alzheimer's Disease." (PMID 32974003, 2020). "Other studies showed that Cystatin C has a role as a susceptibility gene for Alzheimer’s disease." (PMID 32438638, 2020). "A polymorphism in the CysC gene (CST3) is linked to increased risk for Alzheimer's disease (AD)." (PMID 22783166, 2012). "Notably, decreased CSF cystatin C levels have been found to be a critical indicator of rapidly progressive dementia and Alzheimer’s disease, while elevated levels may suggest susceptibility to certain conditions like depression." (PMID 37834128, 2023). "A study in Neurology demonstrated that an increase in cystatin C activity could prevent the development of Alzheimer’s disease, and every 0.1 μmol/L decrease in cystatin C level increased the risk of Alzheimer’s disease by 29% (HR 1.29, 95% CI 1.03−1.63, p < 0.03)." (PMID 37056689, 2023). "Cathepsins that are typically localized in lysosomes, endosomes, or vesicles could be released into the cytoplasm of degenerating neurons and generate an imbalance between cystatin C (inhibitor of proteases) and cathepsins (cysteine proteases), which has been associated to Alzheimer’s disease." (PMID 34528139, 2022). "In Alzheimer's disease (AD), cystatin C has been shown to have a neuroprotective action by inducing autophagy, inhibiting cysteine proteases and by inhibiting amyloid-β aggregation." (PMID 39958955, 2025). "Given the emerging role of B cells in both Alzheimer’s disease and cancer, further studies are warranted to elucidate the regulatory impact of cystatin C oligomers on B-cell function." (PMID 41233352, 2025). "The ubiquitously expressed cystatin C has received more attention in the realm of neurodegenerative diseases, including Alzheimer’s disease, amyotrophic lateral sclerosis (ALS), and MS, for its inhibitory effect on cathepsin B." (PMID 38879499, 2024). "A single nucleotide polymorphism in the leader sequence of precursor cystatin C, encoding an A25T amino acid change resulting in a variant B protein, has been identified as a risk factor not only for AMD, but also Alzheimer’s disease (AD)." (PMID 36899848, 2023). "Cystatin C is a protein commonly utilized as a biomarker for assessing kidney function and Alzheimer’s disease." (PMID 37207178, 2023). "Patients with Alzheimer’s disease, compared to healthy people, are characterized by significantly higher levels of leptin, cystatin C and tau protein, and lower levels of neuropilin-1." (PMID 37959320, 2023). "This study confirmed the involvement of cystatin C in the pathogenesis of Alzheimer’s disease (AD) and cognitive impairment." (PMID 38132490, 2023). "Cystatin C has emerged as a promising prognostic factor for age-related complications, including cardiovascular disease and impaired cognition, such as Alzheimer’s disease (AD)." (PMID 37834128, 2023). "Regarding the current interesting reports about the role of Porphyromonas gingivalis in the course of Alzheimer’s disease, it should be noted that both cystatin C and ovocystatin have antibacterial activity, including Porphyromonas ginigivalis." (PMID 35566501, 2022). "There is convincing evidence that cystatin C plays an important role in aging and Alzheimer’s disease." (PMID 35566501, 2022). "Of note, cystatin C has been reported to co-localize with amyloid-β, which aggregates in the hippocampus and entorhinal cortex in individuals suffering from Alzheimer's disease." (PMID 34616751, 2021). "Other members of the cystatin superfamily, notably cystatin C, are highly expressed in the RPE and are associated with increased risk of AMD and Alzheimer’s disease." (PMID 34440888, 2021). "Cystatin C is indicated to be involved in the pathogenesis of Alzheimer's disease (AD) and cognitive impairment." (PMID 35153722, 2021).
Alzheimer disease (continued). "Recently, CST3 has also emerged as a potential neuron protector in neurodegenerative diseases like Alzheimer’s disease (AD), Parkinson’s disease (PD), and amyotrophic lateral sclerosis (ALS)." (PMID 32733872, 2020). "At least portion of the Aβ released following P. aeruginosa infection of PMVECs is complexed to cystatin C. Previous investigations of cystatin C in Alzheimer's disease have demonstrated that it protects neuronal cells from Aβ toxicity." (PMID 33030263, 2020). "Reduced CHGA (as well as VGF and cystatin C) levels were found in a proteomic analysis of CSF of patients with Alzheimer’s disease." (PMID 22970211, 2012). "Together, Itm2b, Itm2c, Cst3 and Clu potentially ameliorate Alzheimer’s disease." (PMID 38017352, 2024). "It has been widely demonstrated that cysteine protease inhibitor-cystatin C (Cys C) might be a potential target for Alzheimer’s disease treatment." (PMID 35566501, 2022). "Using NEBULA in Alzheimer’s disease cohort data sets, we found that the cell-level expression of APOE correlated with that of other genetic risk factors (including CLU, CST3, TREM2, C1q, and ITM2B) in a cell-type-specific pattern and an isoform-dependent manner in microglia." (PMID 34040149, 2021). "On the contrary, it has been suggested that CST3 is neuroprotective in Alzheimer's disease." (PMID 32582192, 2020). "Similarly, previous reports showed that the related cystatin C inhibited Aβ amyloid assembly in vitro and further inhibited Aβ deposition in mouse models of Alzheimer’s disease suggesting that it plays a protective role in regulating Aβ amyloidogenesis and in disease progression." (PMID 33384380, 2021). "The study for function of Cystatin C in Alzheimer’s disease remains unclear." (PMID 32438638, 2020). "Cystatin C also accumulates in the smooth muscles of the cerebral penetrating arterioles in patients with CAA and Alzheimer's dementia, which might facilitate the dysregulation of the composition of the basement membrane, and the disruption of smooth muscle layer." (PMID 29930507, 2018).
Sepsis (55 papers, 2010 to 2025). Sepsis is defined as life-threatening organ dysfunction caused by a dysregulated host response to infection. "After logistic regression, it was found that RDW, APACHE II score, PCT, IL-6, CRP, and cystatin C were all independent risk factors for AKI in children with sepsis (P<0.05)." (PMID 41281283, 2025). "In conclusion, this study presented a logistic regression-based model combining RDW, APACHE II, and additional biomarkers (PCT, IL-6, CRP, and cystatin C) to predict AKI risk in children with sepsis." (PMID 41281283, 2025). "The LR-based model integrating RDW, APACHE II score, and biomarkers (PCT, IL-6, CRP, cystatin C) effectively predicts the risk of AKI in children with sepsis, offering a valuable tool for early intervention and improved patient outcomes." (PMID 41281283, 2025). "The Cystatin C levels upon admission and at day 3, were the best predictors for the persistence of sepsis-associated AKI and 28-day mortality, respectively." (PMID 38446371, 2024). "In this study we demonstrated that cystatin C-deficient mice were significantly more sensitive to the lethal LPS-induced sepsis." (PMID 34440840, 2021). "The fact that [TIMP-2]·[IGFBP7] are independently associated with AKI in sepsis is a relevant advantage of these biomarkers compared with more widely described NGAL or cystatin-C." (PMID 28884304, 2017). "The association between sepsis and urinary cystatin C has also been observed by others." (PMID 25866432, 2015). "Only sepsis was independently associated with higher cystatin C (by 1.72 mg/L)." (PMID 25866432, 2015). "Besides, higher serum levels of cystatin C at admission were associated with the development of sepsis (34.8% versus 13.8%, P < 0.001) and vasopressor drug use (23% versus 15%, P = 0.01)." (PMID 24967238, 2013). "• In the ICU, urinary cystatin C is independently diagnostic of sepsis." (PMID 20459852, 2010). "Cystatin C could be a relevant residual glomerular filtration rate marker during hemodialysis (HD), and a high cytokine plasma (p) rate is associated with an increase in mortality during sepsis." (PMID 20546598, 2010). "Serum markers such as procalcitonin (PCT), interleukin-6 (IL-6), C-reactive protein (CRP), and cystatin C have been widely studied in the context of sepsis and kidney injury." (PMID 41281283, 2025). "Decrease serum concentrations of creatinine (Cr), blood urea nitrogen (BUN), and cystatin C (Cys-C) in murine models of sepsis." (PMID 41041277, 2025). "By combining RDW and APACHE II score with PCT, IL-6, CRP, and cystatin C, clinicians can obtain a more comprehensive understanding of both the inflammatory and renal aspects of sepsis." (PMID 41281283, 2025). "Serum cystatin-C levels, measured by ELISA, were significantly higher in critically ill patients with sepsis than in controls." (PMID 40724987, 2025). "This is also in line with studies in humans in which serum cystatin C concentrations are increased in patients with sepsis and can potentially act as a biomarker for early diagnosis, to assess severity, and to evaluate the prognosis of this condition." (PMID 38891627, 2024). "Patients with sepsis at admission demonstrated elevated levels of renal retention (cystatin C, urea) and inflammatory parameters." (PMID 38892009, 2024). "Cystatin C, ammonia, and bicarbonate have been described to be biomarkers of sepsis and inflammation in humans." (PMID 38891627, 2024). "In our report, cystatin C is increased in the saliva of pigs with S. suis, which is an infection condition leading to sepsis." (PMID 38891627, 2024). "The correlations between u-Gc/u-creatinine, u-ORM/u-creatinine and u-Cystatin C/u-creatinine suggest that increased u-Gc excretion in sepsis reflects to proximal tubular injury." (PMID 37836706, 2023).